C8orf33 (chromosome 8 open reading frame 33)
Synonyms: FLJ20989
Tractability: PROTAC: ubiquitination databases record sites on it; its protein half-life has been measured.
Gene: Protein-coding gene on chromosome 8 (145,052,425 to 145,066,685, forward strand). Ensembl gene ENSG00000182307.
Subcellular location (Human Protein Atlas): Nucleoplasm; Plasma membrane
Gene Ontology:
Molecular function: protein binding
Genetic constraint (gnomAD): Loss-of-function variants: 28 observed, 26.48 expected, observed/expected ratio (o/e) 1.06, 90% interval 0.78 to 1.45. The upper end of that interval is the gene's LOEUF score, 1.45, which puts it in group 5 of 6, group 1 being the genes least tolerant of losing a copy. Missense variants: 369 observed, 313.23 expected, observed/expected ratio (o/e) 1.18, 90% interval 1.08 to 1.28. Synonymous variants: 153 observed, 125.45 expected, observed/expected ratio (o/e) 1.22, 90% interval 1.07 to 1.39.
Homologues: Orthologues: chimpanzee C8H8orf33 (96% identical), macaque C8H8orf33 (92% identical), mouse 1110038F14Rik (64% identical), rat C7h8orf33 (63% identical), dog C13H8orf33 (60% identical), tropical clawed frog c9h8orf33 (31% identical), zebrafish zgc:112185 (27% identical), Drosophila melanogaster CG14286 (19% identical).
Diseases named in the same sentence as C8orf33 in open-access papers:
C8orf33 is named in the same sentence as 8 diseases in open-access papers, as found by Europe PMC text mining. Sharing a sentence is not in itself a finding about the gene and the disease. The quoted sentences say what the papers report.
acute myeloid leukemia (1 paper, 2023). Acute myeloid leukemia (AML) is a group of neoplasms arising from precursor cells committed to the myeloid cell-line differentiation. "Expression of OGT, C8orf33, DGKA and SMTN has been correlated with cardiovascular disease, hepatocellular carcinoma, acute myeloid leukemia and hypertension, respectively." (PMID 37026480, 2023).
laryngeal carcinoma (1 paper, 2019). Carcinoma that arises from the laryngeal epithelium. "Assessment of these genes in clinical sub-cohorts of TCGA indicated that early stage tongue (MTFR1, C8ORF33, OTUD6B) and laryngeal cancers (TWISTNB, KLHL13 and UBE2Q1) were defined by distinct prognosticators." (PMID 31310629, 2019).
cancer (3 papers, 2019 to 2025). A tumor composed of atypical neoplastic, often pleomorphic cells that invade other tissues. "Since C8orf33 loss leads to rDNA instability, we posit that CX5641 inhibitor sensitizes C8orf33-mutated cancers." (PMID 41249114, 2025). "A search for novel genetic variants of C3orf70, C8orf33, C8orf76 and C8orf82 associated with systemic diseases, including cancers, is of practical interest for medical genomics." (PMID 37373333, 2023). "It is interesting to note that GA frequency is up to 6% in C3orf70, C8orf33, C8orf76 and C8orf82 genes according to the most affected cancer types." (PMID 37373333, 2023). "Five genes were located in four of the seven breakpoint regions and three of these genes (CACNA1B, C8orf33 and KIAA0513) are associated with cancer." (PMID 31249626, 2019). "Interestingly, several studies showed that C8orf33 is overexpressed in various types of cancers." (PMID 41249114, 2025).
tumor (3 papers, 2017 to 2019). "This yielded 88 genes associated with tumor grade, in which seven DEGs (C8orf33, TSNAXIP1, TM4SF1, CTH, ANXA2, KIAA1522 and LRRC1) can distinguish HCC of G3 from G1, two DEGs (CYB5A and RRAGD) can distinguish HCC of G3 from G2, and two DEGs (CFHR4 and F13B) can distinguish HCC of G3 from G4." (PMID 29123978, 2017). "Interestingly, only C8orf33 and NBEA seemed to have tumor suppressor functions." (PMID 31249626, 2019).
C8orf33 also shares sentences with these, for which no sentence is quoted: cardiovascular disease (1 paper); hepatocellular carcinoma (1); Hypertension (1); tongue cancer (1).